EZR (ezrin)
Diseases named in the same sentence as EZR in open-access papers (continued):
Sharing a sentence is not in itself a finding about the gene and the disease.
osteosarcoma (continued). "The significance of ezrin immunoexpression and prognosis for osteosarcoma is still controversial." (PMID 23805177, 2013). "Furthermore, miR-183 has been found to be capable of regulating Ezrin protein (a member of the family with similarity to Merlin) in osteosarcoma and lung cancer." (PMID 23776562, 2013). "Ezrin has been found to be upregulated in osteosarcoma by several research groups." (PMID 22550414, 2012). "Overexpression of ezrin, a protein known to play a key role in cancer metastasis, has already been shown to result in disease progression and metastasis in a number of cancers including osteosarcomas and rhabdomyosarcomas." (PMID 22736953, 2012). "It has been reported that Ezrin is required for metastasis and recurrence of osteosarcoma." (PMID 22922800, 2012). "Ezrin expression was positively correlated to migration and invasion of osteosarcoma cells." (PMID 22922800, 2012). "This suggests that miR-183 may possibly play a tumor suppressor role in the metastasis of osteosarcoma by downregulating Ezrin expression levels." (PMID 22922800, 2012). "By downregulating the Ezrin expression level, miR-183 might act as a significant inhibitory factor in the progression of osteosarcoma cells." (PMID 22922800, 2012). "In a cDNA microarray study of osteosarcoma, EZR was also identified as a highly expressed gene in osteosarcomas, and that study suggested that EZR may have an important role in metastasis." (PMID 23226966, 2012). "In addition, two articles that compared the EZR expression in high- and low-grade human osteosarcoma tumor samples demonstrated a clear correlation between ezrin expression and survival." (PMID 23226966, 2012). "Further studies have indicated that suppression of ezrin protein function abrogates pulmonary metastases of murine rhabdomyosarcoma and osteosarcoma cells, suggesting that ezrin may be a key regulatory molecule in malignant disease." (PMID 15987432, 2005). "Likewise, ezrin exhibited strong expression in a variety of invasive human cancers, including osteosarcomas, melanomas, astrocytic tumours, and pancreatic, lung and endometrial carcinomas." (PMID 15987432, 2005). "Thus, RGS12 might suppress osteosarcoma growth by regulating the RhoA/YAP/TEAD1/Ezrin signaling pathway." (PMID 40271194, 2025). "Additionally, RhoA expression has been correlated with Ezrin expression in osteosarcoma, where Ezrin expression may modulate RhoA expression." (PMID 37371090, 2023). "Therefore, miR211 could suppress the osteosarcoma cell proliferation ability via the targeted regulation of EZRIN." (PMID 31333725, 2019). "In addition, this meta‐analysis is a retrospective study, and most of the included studies investigated the clinical significance of ezrin expression in patients with osteosarcoma (12 of 19), which might lead to subject selection bias." (PMID 31376222, 2019). "Regarding the correlation between ezrin expression and CP, the results of the pooled data analysis showed that ezrin overexpression was significantly correlated with an increased rate of tumor metastasis and recurrence, which was specifically notable for osteosarcoma." (PMID 31376222, 2019). "The findings of our tests revealed that adenovirus-mediated siRNA targetting ezrin can inhibit the proliferation, migration, and invasion of MG-63 cells, and induce apoptosis of MG-63 cells, which has certain reference value in the gene therapy for the metastasis of human osteosarcoma." (PMID 29899165, 2018). "Furthermore, Ezrin-mediated early metastasis was partially dependent on activation of the ERK/mitogen-activated protein kinase (MAPK) pathway in osteosarcoma, while depletion of Ezrin down-regulated the MAPK and transforming growth factor-β pathways in esophageal squamous cell carcinoma." (PMID 26933912, 2016).
osteosarcoma (continued). "Ezrin is the only other protein associated with metastasis in osteosarcoma, and this relationship was confirmed in this study (P<0.001), with negative correlations observed between the expression of Ezrin and RanBP9 or TSSC3 (P<0.001)." (PMID 28032865, 2016). "Imaging characteristics of children with osteosarcoma combined with KI67 and Ezrin gene expression were used to establish a model that can accurately predict cell metastasis in this context." (PMID 37791063, 2023). "Pioneering research on the therapeutic benefits of ezrin inhibition in osteosarcoma (OS) initially identified two small molecules, NSC50787 and NSC668394, which both dephosphorylate ezrin at its Thr567 residue, leading to inactivation." (PMID 33005093, 2020). "In conclusion, our observations demonstrated that adenovirus-mediated siRNA targetting ezrin can inhibit the proliferation, migration, and invasion of MG-63 cells, and induce apoptosis of MG-63 cells, which may be clinically helpful to cancer gene therapy for osteosarcoma treatment." (PMID 29899165, 2018). "Evaluation of 459 patients revealed higher frequency of ezrin expression in stage III and stage IV than in lower histological stages of osteosarcoma." (PMID 28061797, 2017). "Recent literature data suggested that in osteosarcoma the panel of expression of PLC isoforms varies in a complex and unclear manner and is related to ezrin, probably networking with Ras GTPases, such as RhoA and Rac1." (PMID 27026853, 2016). "We analyzed the expression and the subcellular localization of PLC enzymes in cultured human osteosarcoma MG-63 cells, commonly used as an experimental model for human osteoblasts, using U-73122 PLC inhibitor, U-73343 inactive analogue, and by silencing ezrin." (PMID 27026853, 2016). "Characteristics of eligible studies evaluating ezrin expression and OS or EFS in osteosarcoma patients." (PMID 23805177, 2013). "We and others have reported that Ezrin is a critical regulator of metastasis in RMS and osteosarcoma, and our data now show that HDACis and DNA demethylating agents can restore Ezrin expression." (PMID 20856924, 2010). "In particular, Ezrin was determined to be a critical regulator of metastasis in pediatric sarcomas such as rhabdomyosarcoma (RMS) and osteosarcoma." (PMID 20856924, 2010). "Furthermore, Ezrin small molecule inhibitors like NSC 305787 and NSC 668394, initially employed in osteosarcoma treatment, hold potential for PCa therapy by hindering Ezrin phosphorylation and its interaction with actin." (PMID 39055653, 2024). "Melanomas and osteosarcomas have no epithelial growth pattern, thus indicating Ezrin’s impact on EMT, specifically tumor cell polarization, adhesion, and migration in those tumor entities." (PMID 36142656, 2022). "As was the case for the analyses of survival outcomes, subgroup analyses according to tumor type (osteosarcoma vs. nonosteosarcoma) were performed to evaluate the correlation between ezrin expression and CP." (PMID 31376222, 2019). "Osteosarcoma cells transfected with C-terminal constitutively active ezrin are not able to form primary tumors and its migration to other tissues (metastasis) is inhibited." (PMID 29209287, 2017). "Our previous experience in osteosarcoma detected Ezrin immunoreactivity in the majority of patients with non-metastatic osteosarcoma of the extremity and revealed that the cytoplasmatic pattern was associated with good prognosis." (PMID 25613038, 2015). "In our series the majority of SS were positive to Ezrin revealing that expression and distribution pattern of staining (cytoplasmatic/membraneous) was not as relevant for prognosis as in osteosarcoma." (PMID 25613038, 2015). "A meta-analysis reveals that patients with positive ezrin have shorter overall survival than negative ezrin patients, suggesting that ezrin may be a potential prognostic marker in osteosarcoma patients." (PMID 36077137, 2022).
osteosarcoma (continued). "siRNA targeting Ezrin, a cytoplasmic peripheral protein involved in metastatic spreading of osteosarcoma and dependent on PIP2, also resulted in PLCγ2 upregulation in human osteosarcoma cell lines, while another study of osteosarcoma cell lines found PLCγ2 to be a differentially regulated gene." (PMID 34157287, 2021). "Moreover, subgroup analysis according to tumor type showed that ezrin overexpression could predict poor OS and MFS in both osteosarcoma and nonosteosarcoma, even though most of the data were from patients with osteosarcoma." (PMID 31376222, 2019). "However, ezrin overexpression failed to predict poor EFS in osteosarcoma (HR 1.20, 95% CI: 0.74–1.96, P = 0.46, PFDR = 1.38, random‐effects), which might have been caused by the limited number studies used and indicates the presence of obvious heterogeneity." (PMID 31376222, 2019). "For example, Ezrin‐mediated early metastatic survival was partially dependent on the activation of MAPK, but not AKT in osteosarcoma." (PMID 32281236, 2020). "While the pattern of ezrin expression in EWS has not previously been reported, data from osteosarcoma tumor samples showed that a cytoplasmic expression pattern occurs in 49% and was correlated with a more favorable prognosis." (PMID 28246524, 2017).
pancreatic cancer (40 papers, 2010 to 2025). "One of these actin-associated proteins, ezrin, is overexpressed in pancreatic cancer and plays a role in invasion and metastasis." (PMID 23152778, 2012). "Ezrin overexpression was also been observed in borderline lesions and pancreatic cancer tissues and associated with tumor malignant transformation and metastatic potential; however, its role and mechanisms remain elusive." (PMID 20569470, 2010). "In addition, 187 pancreatic cancer samples were analyzed and overexpression of Ezrin and YAP (Yes-associated protein) was observed and correlated with a poor prognosis." (PMID 35954398, 2022). "Moreover, Ezrin is responsible for cellular polarization in pancreatic cancer associated macrophages." (PMID 33240887, 2020). "Moreover high expression of Ezrin is associated with poor prognosis in different cancers including pancreatic cancer." (PMID 26840568, 2016). "In pancreatic carcinomas, a high-level ezrin expression is associated with high metastatic potential; membrane translocation of ezrin might play a role in the progression from borderline tumor to malignant transformation." (PMID 20569470, 2010). "Phosphorylation of moesin has been shown to be important for podosome rosette formation in Src-transformed fibroblasts; while in pancreatic cancer cells, ezrin regulates podosome organization independently of its activation." (PMID 41143651, 2025). "Among them, the anti-TAA autoantibodies of CFL1, EZR, CYPA have been shown diagnostic potential in esophageal cancer, pancreatic cancer, and breast cancer." (PMID 38684875, 2024). "Similar to the results of this study, the anti-TAA autoantibodies of CFL1, EZR, CYPA have been shown certain diagnostic performance in esophageal cancer, pancreatic cancer, and breast cancer." (PMID 38684875, 2024). "Some authors debrided DPYSL3 as a metastasis suppressor, while others reported it facilitates pancreatic cancer cell dissemination via a strong interaction with other cell adhesion factors, including Ezrin, focal adhesion kinase and c-SRC." (PMID 36870971, 2023). "In pancreatic cancer, Ezrin was shown to accelerate cancer proliferation and metastasis by activating the FAK/AKT signaling pathway and upregulating FAK expression." (PMID 37371090, 2023). "In our previous study, we found abundant expression of ezrin (EZR) in sEVs extracted from pancreatic cancer cell lines and in the plasma of PDAC." (PMID 37171030, 2023). "We found that Ezrin knockdown inhibited KYSE150 cell proliferation and migration, consistent with the findings of a study where Ezrin gene knockout decreased proliferation and migration of pancreatic cancer cells." (PMID 37791063, 2023). "YAP and ezrin are overexpressed in pancreatic cancer, and their expression correlates with poor prognosis in pancreatic cancer patients." (PMID 35328667, 2022). "Ezrin promotes pancreatic cancer cell proliferation and invasion through the interaction with and nuclear translocation of YAP." (PMID 35328667, 2022). "EZR has been shown to promote tumour progression by modulating the nuclear translocation of YAP in pancreatic cancer and by overexpression in glioblastoma by inactivating the NF2 tumour suppressor, which leads to tumour growth." (PMID 35075167, 2022). "We found EZR was upregulated in pancreatic cancer tissue compared to paracancer tissue by bioinformatics analysis, then we verified the EZR was overexpressed in PC samples by analyzing our PC tissues." (PMID 34627255, 2021). "Whereas both moesin and radixin were found upregulated in lymph node metastases of pancreatic cancer, the level of ezrin expression was unaffected, but its phosphorylation status did change." (PMID 26983550, 2016). "Using this approach, serum autoantibodies to Ezrin were shown to develop early in the pancreatic cancer murine model and also in human patients with PDAC." (PMID 26840568, 2016).
pancreatic cancer (continued). "Overexpression of Ezrin also promoted cell protrusion, microvillus formation, anchorage-independent growth, motility and invasion in the pancreatic cancer cell line, MiaPaCa-2." (PMID 23039327, 2012). "For example, MSN knockdown pancreatic cancer cells showed increased migration, invasion, metastasis and extracellular matrix organization, and EZR was found to be involved in the process of invasion of endometrial cancer cells." (PMID 21448288, 2011). "In this study, we investigated the effect of ezrin on the motility and invasion ability of the pancreatic cancer cell line MiaPaCa-2, as well as the expression of ezrin in pancreatic duct adenocarcinoma, chronic pancreatitis and normal pancreatic tissues." (PMID 20569470, 2010). "To study the role of ezrin in pancreatic cancer, we analyzed its expression pattern in 70 PDAC patients and 61 normal pancreatic or paraneoplastic tissues (more than 1.5 cm away from the tumor)." (PMID 20569470, 2010). "We found that ezrin overexpression promoted cell protrusion, microvillus formation, anchorage-independent growth, motility and invasion in a pancreatic cancer cell line, MiaPaCa-2, whereas ezrin silencing resulted in the opposite effects." (PMID 20569470, 2010). "Ezrin can interact with cortactin to form podosomal rosettes in pancreatic cancer cells, thereby playing a role in pancreatic cancer invasion." (PMID 20569470, 2010). "Additionally, the Ezrin gene enhancer exhibits enhanced transcriptional activity in pancreatic cancer." (PMID 37791063, 2023). "Previous studies showed p-ezrin directly promotes cell mobility and migration in cancer cell lines through the activation of different signaling pathways, including Rac1, CD44 and Cdc42, while in pancreatic cancer ezrin activates FAK/Akt to promote proliferation." (PMID 36926194, 2023). "In pancreatic cancer cells, Ezrin translocates into plasma membranes, binds to increasing amounts of cortactin, and formes a highly ordered structure called a podosomal rosette, which enables epithelial cancer cells to adhere to the underlying substrate and modify their cytoskeletal behaviors." (PMID 33240887, 2020). "Furthermore, proteins that are encoded by the YAP-regulated genes EZR and IGFBP2 (ezrin and IGFBP2, respectively) promote metastasis and epithelial-to-mesenchymal transition (EMT) in pancreatic cancer cells." (PMID 29682330, 2018). "Our previous studies confirmed that phosphorylated Ezrin could mediate EMT in pancreatic cancer cells through the FAK pathway and promote invasion and metastasis." (PMID 28423676, 2017). "A recent study showed that serum autoantibodies against Ezrin could be detected in patients with pancreatic cancer." (PMID 28298808, 2017). "Moreover, ezrin expression rate was 32.4%, but higher for ezrinTyr353 (41.2%) in intestinal-type pancreatic neoplasms." (PMID 24629131, 2014). "A previous study also detected a dramatic reduction in the number of pancreatic cancer cells with podosomal rosettes after ezrin RNAi treatment and reported that formation of podosomes and their rosettes was driven by an ezrin–cortactin interaction, which has a role in pancreatic cancer invasion." (PMID 23357878, 2013). "We next examined whether ezrin can affect the invasion activity of pancreatic cancer cells by the Matrigel invasion assay." (PMID 20569470, 2010). "We propose that ezrin might play functional roles in modulating morphology, growth, motility and invasion of pancreatic cancer cells, and that the Erk1/2 pathway may be involved in these roles." (PMID 20569470, 2010). "Ezrin was not detectable in normal pancreatic ducts and acini; however, 64 PDAC samples were found to be ezrin positive (91.4%, 64/70), suggesting that ezrin was overexpressed in human PDAC and that ezrin expression was likely associated with pancreatic cancer development." (PMID 20569470, 2010).
pancreatic cancer (continued). "In pancreatic precancerous lesions, such as PanINs and chronic pancreatitis, blocking ezrin function may have therapeutic effects that prevent these two diseases from progressing to pancreatic cancer." (PMID 20569470, 2010). "The results showed that Ezrin could play a role in regulating angiogenesis in pancreatic cancers." (PMID 35954398, 2022). "EZR links the plasma membrane to the actin cytoskeleton and has been found to regulate podosomal rosette formation together with CTTN in pancreatic cancer cells." (PMID 32984315, 2020). "In the present study, we found that the levels of phosphorylation of EZR and c-Src are regulated by DPYSL3 in pancreatic cancer cells." (PMID 24339867, 2013). "Immunohistochemical analysis demonstrated that ezrin expression was elevated in PDAC samples compared to normal pancreatic tissues, which provided additional evidence supporting a functional role of ezrin in pancreatic cancer development." (PMID 20569470, 2010). "In CAPG-overexpressing pancreatic cancer cells, phosphorylation status of other actin-modulating proteins (cofilin, ezrin/radixin) was not significantly altered, suggesting possible involvement of other cellular proteins, such as ornithine aminotransferase and enolase." (PMID 31360146, 2019).